IL1R1 (interleukin 1 receptor type 1)
Diseases named in the same sentence as IL1R1 in open-access papers (continued):
Sharing a sentence is not in itself a finding about the gene and the disease.
Obesity (34 papers, 2013 to 2025). Accumulation of substantial excess body fat. "Although Akkermansia muciniphila is associated with improvements in obesity and insulin resistance, we observed an unexpected increase in this species in both WT and IL-1R1-deficient mice that developed obesity." (PMID 39203559, 2024). "The HFD induced obesity in both WT and KO groups; however, the deficiency of IL-1R1 resulted in the exacerbation of obesity, proved by the significant increase in adiposity index." (PMID 39203559, 2024). "Both leptin resistance and the absence of the receptor that mediates most of the actions of this interleukin (IL-1R1) are associated with obesity." (PMID 36674935, 2023). "The underlying molecular mechanism of celastrol anti-obesity and increase the leptin sensitivity can be attributed to Sirtuin 1(Sirt1), interleukin-1 receptor 1(IL1R1), protein tyrosine phosphatase (PTP) 1B (PTP1B), and T-cell PTP (TCPTP)." (PMID 35444532, 2022). "A KO of the IL1 receptor type 1 gene (Il1r1), which codes for a receptor of IL-1α, IL-1β, and IL-1RN, causes maturity onset obesity on a normal diet but reduces local adipose-tissue inflammation on an HFD despite almost unchanged immune-cell recruitment." (PMID 34834553, 2021). "For example, IL-1R1 deficient mice develop mature onset obesity while IL-1Ra KO mice are leaner than their littermates." (PMID 25244011, 2014). "When we analysed the association of the EQ-5D-3L usual activity dimension with sex, age, BMI, and genetic polymorphisms of IL-1R1 and IL-1RN, the EQ-5D-3L usual activity dimension had an association with older age (OR = 2.3, 95% CI: 1.2–4.5) and obesity (OR = 3.0, 95% CI: 1.1–8.0)." (PMID 37198429, 2023). "Considering the involvement of neural IL1R1 in celastrol-dependent anti-leptin resistance it is reasonable to postulate that IL1R1 is complicatedly implicated in the protection of celastrol against obesity through both central and peripheral mechanisms." (PMID 36009315, 2022). "However, recently IL1R1 has been identified as one of the key mediators in leptin sensitivity and IL1R1 deficiency leads to a higher degree of obesity and metabolic disturbance." (PMID 34372849, 2021). "Similarly, mice deficient in IL-1α are protected against obesity-induced glucose intolerance; therefore, the blockade of IL1R1 and IL-1α could be used in the treatment of IR and obesity." (PMID 32012695, 2020). "It has been found that knockdown of IL‐1R1‐expressing CX3CR1+ cells in mice with dietary obesity can eliminate the cognition and restore the immunoquiescence of microglia in hippocampus, proving the pivotal role of neuroinflammation." (PMID 34951130, 2022). "Administering IL1R1 inhibitor (anakinra) to celastrol-treated mice also attenuated the anti-obesity effects of celastrol." (PMID 36009315, 2022). "Given the increase in fat mass in the IL1HF group, it is unlikely that IL-1R1 signaling represents a valid target for the effects of maternal HFD diet on developmental programming of obesity." (PMID 32655404, 2020). "The IL-1 signaling pathway represents a point of intersection between metabolic and inflammatory systems, with previous work demonstrating a protective metabolic effect of IL-1R1 depletion in young male mice exposed to diet-induced obesity." (PMID 32655404, 2020). "Previous studies have demonstrated that deletion of IL-1R1 signaling prevents the onset of IR in a mouse model of diet-induced obesity." (PMID 32655404, 2020). "In fact, IL1R1 has been identified as a mediator that increases leptin sensitization secondary to the action of celastrol, an effective drug treatment of obesity." (PMID 32824322, 2020). "Other inflammatory markers such as interleukin-1 receptor-1 (IL1R1) and its ligand, IL1β, are upregulated in cardiovascular disease, obesity, and infection." (PMID 25949827, 2015). "Interleukin-1 receptor-1 (IL1R1) and its ligand, IL1β, are upregulated in cardiovascular disease, obesity, and infection." (PMID 25949827, 2015).
Obesity (continued). "Knock out models suggest that abolition of IL-1β or its receptor IL-1R1 partially protects against obesity-induced metabolic disease." (PMID 23844177, 2013). "Additionally, IL-1R1-deficient mice consuming an HFD diet exhibited exacerbated intestinal permeability and bacterial translocation, concomitant with worsening obesity and glucose intolerance." (PMID 39203559, 2024). "Furthermore, this receptor mediates leptin resensitisation after the administration of celastrol, a potent anti-obesity agent, with the physical interaction between ObRb and IL-1R1 being the molecular mechanism involved." (PMID 36674935, 2023). "Whereas knockout of Il-1r1 gene causes leptin resistance and obesity, Ptpn1 knockout results in negative energy balance, protection from weight gain and improved insulin sensitivity." (PMID 29371411, 2018). "In conclusion, we found that IL-1R1 is associated with a reduction in ILC3 cells in the small intestine, which may result in reduced IL-22 expression, leading to a worsening of obesity and MS due to increased intestinal permeability and bacterial translocation to the VAT." (PMID 39203559, 2024). "The current study demonstrates that hepatocyte‐specific loss of the IL‐1R1 does not affect the development of obesity or NAFLD from a high‐fat, high‐carbohydrate diet (HFD) but led to a significant reduction of hepatocyte injury and improved both hepatic and whole‐body insulin sensitivity." (PMID 36101976, 2022). "Further, we investigated in more detail selected DMRs in TSC22D1, HAS2, GCC1, NCKIPSD from SAT, all being hypermethylated in individuals with obesity and BCCIP, IL1R1 (hypermethylated in lean) and FMNL2 (hypermethylated in individuals with obesity) from OVAT." (PMID 41225618, 2025). "These included IL1R1 (hypermethylated among lean), FMNL2 (hypermethylated in obesity) in OVAT and TSC22D1 (hypermethylated in obesity) in SAT." (PMID 41225618, 2025). "This study investigates the role of IL-1R1 in inducing ILC3 cells and conferring protection during obesity and MS." (PMID 39203559, 2024). "Based on this evidence, our hypothesis is that IL-1, via IL-1R1, promotes the induction of intestinal ILC3 cells and reinforces the intestinal barrier through of the production of IL-22, as well as the improvement of metabolic and inflammatory changes associated with obesity and MS." (PMID 39203559, 2024). "It has been theorized that the observed association of IL1 cytokine family genes with obesity in mice may be due to leptin dysregulation and consequent hyperphagia rather than direct modulation of adipocyte function because Il1r1 and Il6 KO mice develop leptin resistance." (PMID 34834553, 2021). "In support of this, it was shown that IL1R1 expression was downregulated in OVAT of individuals with obesity and type 2 diabetes compared to non-diabetic controls." (PMID 41225618, 2025). "Overall, inflammation may play the role of a bridge between obesity and Alzheimer’s disease, and the four hub genes above (MMP9, PECAM1, C3AR1, and IL1R1) are critical to this." (PMID 36568118, 2022). "Therefore, we aimed to study the development of obesity and accompanying NAFLD in hepatocyte‐specific IL‐1R1 knockout mice (Il1r1Hep−/–) and their WT littermates." (PMID 36101976, 2022). "A similar effect was observed in IL1-R1 KO mice, suggesting that at high concentrations of IL-1Ra typically observed in obesity, IL-1Ra can contribute to the development of insulin resistance in a mechanism independent of IL-1Ra binding to IL-1R1." (PMID 25244011, 2014). "The authors used a series of dietary obesity and VAT transplantation experiments using Nlrp3−/− mutant mice and Tg mice with inducible deletion of IL1r1 (interleukin 1 receptor type 1) in CX3CR1(CX3C chemokine receptor 1)-expressing cells to verify their hypothesis." (PMID 34070553, 2021).
Obesity (continued). "At high concentrations, as found in obesity, IL-1Ra could have deleterious effects independent of IL-1R1 since IL-1R1 KO mice display improved insulin sensitivity after IL-1Ra knock-down." (PMID 25244011, 2014).
COVID-19 (31 papers, 2020 to 2025). A disease caused by infection with severe acute respiratory syndrome coronavirus 2. "The myocardial injury caused by COVID-19 was associated with multiple inflammatory pathways, and IL6, NFKBIA, CSF1, CXCL1, IL1R1, SOCS3, and CASP1 were key genes of the inflammatory pathway." (PMID 37564653, 2023). "A review study observed that variants in cytokine genes such as IL-1β, IL1R1, IL1RN, IL-6, IL-17A, FCGR2A, and TNF may be associated with disease susceptibility and/or severity, cytokine storm, and/or COVID-19 complications like thrombosis." (PMID 37662953, 2023). "As IL1R1 appears to play a role in COVID-19, MEDI8968 might be a future therapeutic option in patients with severe COVID-19 to prevent overwhelming inflammatory host responses." (PMID 35163504, 2022). "These miRNAs target several pro-inflammatory cytokine and chemokine genes (e.g., TNF, CCL2, CXCL9, CXCL10, IL10, VEGFA) as well as cytokine and chemokine receptors and transduction factors (IL1R1, IL2RA, IFNAR2), reported as upregulated and associated with mortality in COVID-19 patients." (PMID 36032130, 2022). "Variants in cytokine genes such as IL1B, IL1R1, IL1RN, IL6, IL17A, FCGR2A, and TNF could be related to disease susceptibility and cytokine storm, and/or COVID-19 complications (e.g., venous thrombosis)." (PMID 33868239, 2021). "Together, these studies suggest that modulating NLRP3 or IL-1R1 related inflammatory responses could be a successful therapy in COVID-19." (PMID 33916409, 2021). "In the current study, we performed direct comparisons of cytokine expressions in KD and severe COVID and found that the expressions of IL1A, IL1R1, and TNF were about 2.6- to 10-fold higher in severe COVID-19 than in KD." (PMID 36159873, 2022). "Seven out of the 16 known cytokine markers (including IL1A, IL1R1, CCL2, IL6, IL10, CXCL10, and VEGFA) were less pronounced in KD than in severe COVID-19 patients compared to FC and HC, respectively." (PMID 36159873, 2022). "MiRNAs that were downregulated in serum of COVID-19 patients mainly target genes promoting angiogenesis (e.g., VEGFA, ANGPT2, COL4A1, FGF2, ZEB1), apoptosis, autophagy, stress response (e.g., ATG12, ATG14, ATG2B, SOD2, TXNIP), and inflammation (e.g., CXCL9, CXCL10, IL1R1, TNF)." (PMID 36032130, 2022). "In all patients who succumbed to COVID-19, we found increased expression of bone marrow stromal cell antigen 2 (BST2) and interleukin 1 receptor type 1 (IL1R1) independent of hospitalization time." (PMID 35163504, 2022).
colitis (30 papers, 2011 to 2025). Inflammation of the colon. "Notably, IL-1R1 expression is not limited to fibroblasts in colitis; it is also observed in mesenchymal cells during autoimmune diseases, intestinal inflammation, and solid tumors, where it exhibits diverse functions." (PMID 38674054, 2024). "IL-1R exists in two forms, namely, IL-1R1 and IL-1R2, with IL-1R1 being the primary receptor, and IL-1R signaling directly induces chemokine expression and reactive oxygen species-generating genes, which have detrimental effects during epithelial injury-induced colitis." (PMID 40076032, 2025). "Therefore, we hypothesized that elevated Il17a and Il1r1 transcripts in colonic Th17 cells may position RORγtS182A mice to develop exacerbated tissue inflammation in response to elevated IL-1β signaling during DSS-induced colitis." (PMID 35294872, 2022). "Some reports found that IL-1β enhanced colitis severity in animal models, while others reported that Il1β-/- and Il1r1-/-, the IL-1α and IL-1β receptor, mice displayed exacerbated severity in DSS-induced colitis." (PMID 34721422, 2021). "As inhibitors specific to PTX3/Ptx3 activity are not available, we turn to use IL1R1-specific inhibitor anakinra to assess the function of Ptx3 in the TedCH, colitis, and aberrant hematopoiesis." (PMID 40230417, 2025). "IL-1β induces Il33 in colon myofibroblasts in vitro, but signaling through the IL-1R1 is not necessary for induction of IL-33 in DSS-induced colitis." (PMID 33953267, 2021). "Although IL-1β induced IL-33 expression in vitro, using Il1r1−/− mice, we showed this signaling pathway is not required for Il33 induction during DSS-induced colitis." (PMID 33953267, 2021).
Sepsis (30 papers, 2012 to 2026). Sepsis is defined as life-threatening organ dysfunction caused by a dysregulated host response to infection. "Sepsis patients exhibited a distinct pattern, with decreased sIL-1R1 plasma concentrations but markedly increased levels of IL-1R2 and IL-1R1." (PMID 40699828, 2025). "Our study provides a comprehensive analysis of IL-1R1 and IL-1R2 expression across different cell populations and organs during sepsis by analyzing published sc-RNAseq data and flow cytometry." (PMID 41293423, 2025). "To investigate the roles of IL-1R subtypes, specifically IL-1R1 and IL-1R2, in sepsis, we utilized single-cell RNA sequencing (scRNA-seq) and flow cytometry to comprehensively map their expression profiles across various immune cell populations and organs." (PMID 41293423, 2025). "This distinction raises important questions regarding the differential roles of IL-1R1 and IL-1R2 in innate immunity and inflammation during sepsis." (PMID 41293423, 2025). "We reveal distinct and compartmentalized expression landscapes for IL-1R1 and IL-1R2 across organs during sepsis." (PMID 41293423, 2025). "By contrast, NLRP3 and IL-1R1 are required for long-term maintenance of microglial activation after sepsis." (PMID 32070376, 2020). "However, further investigation is needed to elucidate the precise role by which IL-1R1 influences innate lymphoid cell in sepsis." (PMID 41293423, 2025). "Il1r1 encodes the interleukin-1 receptor type 1, which has been shown to be critical for synaptic plasticity and neuroinflammation and is induced in hippocampal neurons during CLP sepsis, but which may also be highly expressed in inflamed endothelial cells." (PMID 26790027, 2016). "In the two groups of different expression trend modules, the core genes such as CD160, GATA2, GNLY, IL2RB and TGFBR3 were downregulated in the sepsis group, while genes such as ELANE, IL1R1, TLR5, FCGR1A, MAPK14 and PCSK9 were upregulated." (PMID 35332254, 2022). "Notably, our study also identifies a unique expression pattern of IL-1R1 in ILC2 in the intestine tissues under both healthy and sepsis condition." (PMID 41293423, 2025). "Expression levels of Selp, Ccl2 and Il1r1 were robustly increased by CLP sepsis irrespective of genotype, suggesting that endothelial MyD88 is not required for transcriptional responses to CLP in hippocampal vasculature, microglia and neurons." (PMID 26790027, 2016). "We found that IL-1R1 was predominantly expressed on non-immune cells (lung fibroblasts, liver endothelial cells and heart fibroblasts), and showed increased changes during sepsis." (PMID 41293423, 2025). "Thus, sepsis still launches acute proinflammatory response in the brain without the participation of NLRP3 or IL-1R1." (PMID 32070376, 2020). "We found higher levels of IL-1β, C3AR1, and IL1R1 transcripts in patients with sepsis and a positive correlation between expression levels of IL-1β and C3AR1 in sepsis patients but not healthy controls." (PMID 38236896, 2024).
epilepsy (29 papers, 2010 to 2025). A brain disorder characterized by episodes of abnormally increased neuronal discharge resulting in transient episodes of sensory or motor neurological dysfunction, or psychic dysfunction. "IL-1β interacts with its specific receptor IL-1R1, implicated in neuroinflammation response in epilepsy pathogenesis." (PMID 38087170, 2024). "VX-765 is a reversible caspase-1 inhibitor that blocks IL-1β maturation and suppresses IL-1β/IL-1R1 signaling, a pathway critically involved in drug-resistant epilepsy via neuroinflammation and blood–brain barrier disruption." (PMID 41155637, 2025). "Among these, TNF‐α, IL‐1β levels and its receptor IL‐1R1 in human serum have been suggested to correlate with the severity of epilepsy." (PMID 39907034, 2025). "The expression of IL-1β and its receptor, IL-1R1, is significantly upregulated in postoperative focal brain tissues of epilepsy patients and in various animal models of epilepsy." (PMID 41306289, 2025). "In contrast, IL-1R1 knockout mice exhibited elevated seizure thresholds and reduced seizure severity in experimental epilepsy models." (PMID 41306289, 2025). "Here, we indicated endothelial IL-1R1 is involved in neuroinflammation, facilitating epilepsy progress via Nrf2/HO-1/NLRP3." (PMID 38087170, 2024). "In conclusion, our findings emphasized the critical role of endothelial IL-1R1 in mediating pathogenesis in epilepsy." (PMID 38087170, 2024). "For instance, interleukin‐1β (IL‐1β) and its receptor IL‐1R1 have been reported both in human epilepsy foci and in experimental models of seizures and epilepsy." (PMID 36440924, 2023). "The most convincing evidence supporting the involvement of cytokines in epileptogenesis and epilepsy progression originated from studies on IL-1β, its corresponding receptor (IL-1R1) and its antagonist (IL-1RA)." (PMID 35625063, 2022). "IL-1 receptor type 1 (IL-1R1)/TLR4 pathway is a potential therapeutic target for disease-modifications in patients with epilepsy." (PMID 33105652, 2020). "The successful rates of developing epilepsy by kindling stimuli in the IL-1R1 +/+ and IL-1R1 −/− were 84.6 (11 out of 13) and 72.2% (13 out of 18), respectively." (PMID 27875989, 2016). "In endothelial IL-1R1-CKO KA mice, the number of c-Fos + cells significantly declined after epilepsy modeling when compared to the WT KA group, showing deletion of endothelial IL-1R1 may contribute to the decline of neuronal activation." (PMID 38087170, 2024). "We hypothesized endothelial IL-1R1 serves as a pivotal mediator inducing neuroinflammation in the progression of epilepsy." (PMID 38087170, 2024). "IL1R1 was higher in the epilepsy group than in the control group." (PMID 37061663, 2023). "It has been suggested that IL-1β/ IL-1R1 expression correlates with epilepsy severity." (PMID 35837232, 2022). "In comparison with the epilepsy group, the seizure frequency, duration, and seizure power, the mRNA and protein expressions of IL-1β and IL-1R1, the expressions of RhoA and ROCK I proteins, and the ratio of RhoA protein between membrane and cytosol decreased in the electrical stimulation group." (PMID 35119588, 2022). "We herein hypothesized that IL-1R1 mediates the pathogenesis of epilepsy and the epilepsy-induced sleep disturbances." (PMID 27875989, 2016). "However, our other study demonstrated that IL-1R1 contributes to the epileptogenesis when epilepsy is induced by pentylenetetrazol (PTZ) (personal unpublished result)." (PMID 27875989, 2016). "We herein hypothesized that IL-1 receptor type 1 (IL-1R1) mediates the pathogenesis of epilepsy and epilepsy-induced sleep disturbances." (PMID 27875989, 2016). "The involvement of IL-1r1 in both regions is intriguing, suggesting that this specific cytokine may be instrumental in epilepsy generated by eFSE." (PMID 26730400, 2015).